RPS20 (ribosomal protein S20)
Description:
Component of the small ribosomal subunit. The ribosome is a large ribonucleoprotein complex responsible for the synthesis of proteins in the cell.
Synonyms: S20; uS10
Tractability: Small molecule: an approved drug acts on it; a structure with a bound ligand is known; a high-quality ligand is known. PROTAC: UniProt records ubiquitination sites on it; ubiquitination databases record sites on it; its protein half-life has been measured; a small molecule that binds it is known. Other modalities: a drug acting on it is in phase 2 or 3 trials.
Target class: Other cytosolic protein
Gene: Protein-coding gene on chromosome 8 (56,067,254 to 56,074,510, reverse strand). Ensembl gene ENSG00000008988.
Subcellular location: Cytoplasm
Subcellular location (Human Protein Atlas): Cytosol; Endoplasmic reticulum
Pathways (Reactome):
Metabolism of proteins: Eukaryotic Translation Termination; Formation of a pool of free 40S subunits; Formation of the ternary complex, and subsequently, the 43S complex; GTP hydrolysis and joining of the 60S ribosomal subunit; L13a-mediated translational silencing of Ceruloplasmin expression; PELO:HBS1L and ABCE1 dissociate a ribosome on a non-stop mRNA; Peptide chain elongation; Ribosomal scanning and start codon recognition; SRP-dependent cotranslational protein targeting to membrane; Translation initiation complex formation; ZNF598 and the Ribosome-associated Quality Trigger (RQT) complex dissociate a ribosome stalled on a no-go mRNA
Disease: SARS-CoV-1 modulates host translation machinery; SARS-CoV-2 modulates host translation machinery; Viral mRNA Translation
Metabolism of RNA: Major pathway of rRNA processing in the nucleolus and cytosol; Nonsense Mediated Decay (NMD) enhanced by the Exon Junction Complex (EJC); Nonsense Mediated Decay (NMD) independent of the Exon Junction Complex (EJC)
Cellular responses to stimuli: Response of EIF2AK4 (GCN2) to amino acid deficiency
Developmental Biology: Regulation of expression of SLITs and ROBOs
Metabolism: Selenocysteine synthesis
Gene Ontology:
Molecular function: MDM2/MDM4 family protein binding; protein binding; RNA binding; structural constituent of ribosome; ubiquitin ligase inhibitor activity
Biological process: cytoplasmic translation; translation
Cellular component: cytoplasm; cytosol; cytosolic ribosome; cytosolic small ribosomal subunit; endoplasmic reticulum; extracellular exosome; membrane; nucleoplasm; ribosome; small ribosomal subunit
Genetic constraint (gnomAD): Loss-of-function variants: 2 observed, 13.08 expected, observed/expected ratio (o/e) 0.15, 90% interval 0.062 to 0.48. The upper end of that interval is the gene's LOEUF score, 0.48, which puts it in group 2 of 6, group 1 being the genes least tolerant of losing a copy. Missense variants: 62 observed, 136.12 expected, observed/expected ratio (o/e) 0.46, 90% interval 0.37 to 0.56. Synonymous variants: 59 observed, 44.58 expected, observed/expected ratio (o/e) 1.32, 90% interval 1.07 to 1.64.
Gene-disease validity (ClinGen):
ClinGen rates the evidence that RPS20 causes each of these diseases.
Lynch syndrome (autosomal dominant): Limited. An autosomal dominant hereditary neoplastic syndrome characterized by the development of colorectal carcinoma and a high risk of developing endometrial carcinoma, gastric carcinoma, ovarian carcinoma, renal pelvis carcinoma, and small intestinal carcinoma.
Homologues: Orthologues: guinea pig RPS20 (100% identical), macaque RPS20 (100% identical), mouse Rps20 (100% identical), rabbit RPS20 (100% identical), rat Rps20-ps10 (100% identical), Drosophila melanogaster RpS20 (82% identical), tropical clawed frog rps20 (81% identical), Caenorhabditis elegans rps-20 (72% identical).